FGFRL1 (fibroblast growth factor receptor like 1)
Description:
Has a negative effect on cell proliferation.
Synonyms: FGFR-5; FGFR5; FHFR
Tractability: Antibody: its Gene Ontology location is reachable by antibodies, with high confidence; UniProt predicts a signal peptide or a membrane-spanning region.
Gene: Protein-coding gene on chromosome 4 (1,008,649 to 1,026,901, forward strand). Ensembl gene ENSG00000127418.
Subcellular location: Membrane
Subcellular location (Human Protein Atlas): Vesicles
Pathways (Reactome):
Signal Transduction: FGFRL1 modulation of FGFR1 signaling
Gene Ontology:
Molecular function: fibroblast growth factor receptor activity; heparin binding; identical protein binding; fibroblast growth factor binding
Biological process: cell-cell adhesion; fibroblast growth factor receptor signaling pathway
Cellular component: cell-cell contact zone; Golgi apparatus; plasma membrane; transport vesicle; membrane
Genetic constraint (gnomAD): Loss-of-function variants: 23 observed, 28.04 expected, observed/expected ratio (o/e) 0.82, 90% interval 0.59 to 1.16. The synonymous counts are far from expectation, so gnomAD's model fits this gene poorly and the ratio says little. Missense variants: 764 observed, 696.93 expected, observed/expected ratio (o/e) 1.1, 90% interval 1.03 to 1.16. Synonymous variants: 408 observed, 315.85 expected, observed/expected ratio (o/e) 1.29, 90% interval 1.19 to 1.4.
Homologues: Orthologues: chimpanzee FGFRL1 (99% identical), macaque FGFRL1 (98% identical), dog FGFRL1 (89% identical), pig FGFRL1 (89% identical), guinea pig FGFRL1 (88% identical), rat Fgfrl1 (86% identical), mouse Fgfrl1 (86% identical), tropical clawed frog fgfrl1 (66% identical), zebrafish fgfrl1a (64% identical), Caenorhabditis elegans igcm-4 (27% identical), Drosophila melanogaster CG31431 (16% identical). Paralogues in human: MCRIP2 (10% identical), MCRIP1 (4% identical).
Diseases named in the same sentence as FGFRL1 in open-access papers:
FGFRL1 is named in the same sentence as 48 diseases in open-access papers, as found by Europe PMC text mining. Sharing a sentence is not in itself a finding about the gene and the disease. The quoted sentences say what the papers report.
lung carcinoma (10 papers, 2020 to 2025). "FGFRL1 is closely associated with the development, progression, invasion, drug resistance, and prognosis of several types of cancer, such as bladder cancer, esophageal cancer, larynx carcinoma, lung cancer, ovarian cancer, pancreatic cancer, and prostate cancer." (PMID 40699684, 2025). "In most cases, FGFRL1 exhibits to promote the development and progression of tumors including bladder cancer, esophageal cancer, larynx carcinoma, lung cancer, ovarian cancer, and prostate cancer." (PMID 40699684, 2025). "When FGFRL1 was silenced in lung cancer cells, their ability to migrate and invade increased, as well as the expression levels of EMT markers N-cadherin and vimentin." (PMID 38002256, 2023). "Lung CSC-derived exosomal miR-210-3p promoted EMT process of lung cancer cells via binding to 3’-UTR of FGFRL1." (PMID 37789353, 2023). "In another study, cancer stem cell-derived exosomal miR-210-3p bind and inhibit fibroblast growth factor receptor-like 1 (FGFRL-1) to increase vimentin expression in lung cancer cells." (PMID 35573702, 2022). "In order to clarify the relationship between lung CSC‐derived exosomal miR‐210‐3p and FGFRL1, we performed Western blot analysis to measure the expression level of FGFRL1 in lung cancer cells after co‐incubation with lung CSC‐derived exosomes." (PMID 32396269, 2020). "The results of qPCR analysis demonstrated that, among these genes, FGFRL1 was expressed at significantly decreased levels in lung cancer cells transfected with miR‐210‐3p mimic." (PMID 32396269, 2020). "Taken together, our results provide new insights into a potential molecular mechanism whereby lung CSC‐derived exosomal miR‐210‐3p targets FGFRL1 to promote lung cancer metastasis." (PMID 32396269, 2020). "In this study, we demonstrated that lung CSC‐derived exosomes regulated FGFRL1 expression in lung cancer cells via the transfer of miR‐210‐3p." (PMID 32396269, 2020). "For example, miR-210-3p from lung CSCs is involved in lung cancer progression by targeting FGFRL1." (PMID 36302748, 2022). "FGD5-AS1 promotes lung cancer cell proliferation via sponging miR-107 and upregulating FGFRL1." (PMID 34692852, 2021). "Indeed, FGFRL1 silencing in lung cancer cells increased their migratory and invasive potential, whereas its overexpression in lung cancer cells decreased those abilities." (PMID 34638913, 2021). "Furthermore, silencing FGFRL1 with siRNA promoted the migration and invasion of lung cancer cells and up‐regulated expression levels of N‐cadherin, MMP‐9 and MMP‐1, whereas E‐cadherin expression was down‐regulated." (PMID 32396269, 2020). "Our investigation of the molecular mechanism by which lung CSC‐derived exosomal miR‐210‐3p regulates lung cancer metastasis revealed that FGFRL1 may be the functional target of miR‐210‐3p." (PMID 32396269, 2020). "However, it is worth noting that in other types of human cancers, FGD5-AS1 was shown to exert its oncogenic modulation through other ceRNAs, such as miR-302e/CDCA7 axis in colorectal cancer or hsa-miR-107/FGFRL1 in lung cancer." (PMID 32849774, 2020). "This study demonstrated that CSCs, through the release of exosomes rich with miR-210-3p, induce a prometastatic phenotype in lung cancer cells, downregulating FGFRL1, which may act as a metastatic inhibitor, suggesting new possible therapeutic targets in lung cancer." (PMID 34638913, 2021). "However, in FGFRL1‐overexpressing lung cancer cells, metastatic potential decreased markedly." (PMID 32396269, 2020). "In lung cancer, FGFRL1 may act as a tumour suppressor, but further investigation is needed." (PMID 32396269, 2020). "FGFRL1 may be a promising therapeutic target in lung cancer." (PMID 32396269, 2020). "FGFRL1 may be a target of miR‐210‐3p in the regulation of lung cancer metastasis." (PMID 32396269, 2020).
lung carcinoma (continued). "The results of bioinformatics analysis and dual‐luciferase reporter assays further indicated that miR‐210‐3p may bind to fibroblast growth factor receptor‐like 1 (FGFRL1); silencing FGFRL1 enhanced the metastatic ability of lung cancer cells, whereas overexpressing FGFRL1 suppressed metastasis." (PMID 32396269, 2020). "In lung cancer, it has been demonstrated that CSC-derived exosomes can enhance the invasive and pro-metastatic properties of lung cancer cells by transferring miR-210-3p that binds and down-modulates fibroblast growth factor receptor-like 1 (FGFRL1), inducing a mesenchymal phenotype." (PMID 37207158, 2023).
Obesity (7 papers, 2017 to 2025). Accumulation of substantial excess body fat. "Of note, methylome and transcriptome changes in the ZNF331 and FGFRL1 genes in leukocytes underlined the effects of a very-low-calorie ketogenic diet (600–800 kcal/d) on obesity indices." (PMID 37836535, 2023). "In fact, in the same study the most representative genes ZNF533 and FGFRL1, which were differentially methylated after dietary weight loss treatment, were previously identified as an epigenetic signature of adipose tissue associated with obesity, which is reflected in blood leukocytes." (PMID 37614712, 2023). "Moreover, the expression of FGFRL1, PNKD, PODXL, PTPRCAP, SMAD3 and WDR45L based on previously reported data correlated inversely with the methylation levels in the subcutaneous adipose tissue suggesting a potential epigenetic regulation associated to obesity." (PMID 28211912, 2017). "Relevantly, the areas under the ROC curves (AUCs) for FGFRL1, NCAPH2, PNKD, and SMAD3 evidenced excellent and statistically significant efficiencies in discriminating obesity from non-obesity in both the subcutaneous adipose tissue and leukocytes." (PMID 28211912, 2017). "Specifically, the methylation levels of FGFRL1, NCAPH2, PNKD and SMAD3 exhibited excellent and statistically significant efficiencies in the discrimination of obesity from non-obesity status (AUC > 0.80; p < 0.05) and a great correlation between both tissues." (PMID 28211912, 2017). "Altered DNA methylation in promoters of transcription factor genes (PPARA, KLF15, NR3C1, RORA and ATF4) known to regulate FGF21 expression and its binding receptors and co-factors (FGFR1, FGFR3 and FGFRL1 and KLB) has been revealed in relation to the elevated levels of circulating FGF21 in obesity." (PMID 33670024, 2021).
ovarian carcinoma (7 papers, 2015 to 2025). A malignant neoplasm originating from the surface ovarian epithelium. "The loss of FGFRL1 function significantly affects the proliferation, apoptosis, and migration of ovarian cancer cells in vitro and tumor growth in vivo." (PMID 34777635, 2021). "FGFRL1 would be significantly upregulated in patients with ovarian cancer, and high FGFRL1 expression is associated with a poor prognosis." (PMID 34777635, 2021). "FGFRL1-null mice die in infancy with diaphragmatic defects and renal agenesis, and there are case reports of FGFRL1 mutations in human disease: craniosynostosis and ovarian cancer." (PMID 26224133, 2015). "It was also found that the knockdown of FGFRL1 significantly inhibited cell proliferation in ovarian cancer (OC) cells." (PMID 40699684, 2025). "It was observed that the silencing of FGFRL1 increased the apoptosis rate of ovarian cancer (OC) cells." (PMID 40699684, 2025). "Subsequently, FGFRL1 upregulates Gil1 and activates the Hedgehog (Hh) pathway, thereby promoting the growth, proliferation, and migration of ovarian cancer cells." (PMID 37750089, 2023). "FGFRL1 has been reported to have elevated expression in small cell lung cancer, oral squamous cell carcinoma, ovarian carcinoma, and prostate cancer." (PMID 37750089, 2023). "Increased expression of FGFRL1 in ovarian cancers correlates with poor prognoses for ovarian cancer patients." (PMID 35053442, 2022). "Herein, we analyzed the expression pattern and clinical significance of FGFRL1 in ovarian cancer and tried to detect important pathways as well as key genes in order to understand the mechanism of FGFRL1 contributing to the development of ovarian cancer." (PMID 29675438, 2018). "Through screening of 241 different human tumors with the help of a profiling array and quantitative PCR, it is revealed that FGFRL1 aberrant expression might contribute to the development and progression of ovarian cancer (OC)." (PMID 40699684, 2025). "Here, for the first time, we demonstrated the roles of FGFRL1 in ovarian carcinoma (OC)." (PMID 29675438, 2018). "However, little is known about cellular functions of FGFRL1 in ovarian carcinoma." (PMID 29675438, 2018). "Indeed, it is possible that, in PCa, due to the loss of membranous FGFRL1, re-localized FGFRL1 fails to regulate FGFR signaling through the decoy receptor function and/or adopts other functions to promote PCa progression, as happens, for example, in ovarian cancer." (PMID 35053442, 2022).
Hypertension (6 papers, 2021 to 2025). The presence of chronic increased pressure in the systemic arterial system. "Gene mutation and abnormal expression of Fgfrl1 are demonstrated to correlate with human disease including congenital disease, hypertension, osteoporosis, degenerative diseases of the central nervous system, and different kinds of tumors." (PMID 40699684, 2025). "We performed an association study to investigate the role of FGFRL1 in hypertension, osteoporosis, and height determination in humans." (PMID 35980984, 2022). "Most previous genetic association studies analyzed the association of FGFRL1 with bone formation or bone density, and seldom with hypertension." (PMID 35980984, 2022). "In conclusion, we have replicated the association between FGFRL1 and height, hypertension, and osteoporosis in the Korean population, and found genetic variants associated with each trait." (PMID 35980984, 2022). "The FGFRL1 gene was found to be associated with height, hypertension, and osteoporosis, consistent with the results of a previous study." (PMID 35980984, 2022). "Mice carrying the giraffe-type FGFRL1 allele showed resistance to hypertension and high bone mineral density, suggesting that the genetic changes induced pleiotropic effects related to cardiovascular development and bone formation." (PMID 35980984, 2022). "Accordingly, the results of this replication study, which indicate that the genetic differences influence the risk of osteoporosis and hypertension, provide insight into the role of the FGFRL1 gene while supporting previous functional studies." (PMID 35980984, 2022). "When the giraffe mutation was inserted into the FGFRL1 gene in mice, significantly less renal and heart fibrosis was observed during hypertension." (PMID 34367673, 2021). "Genetic variants in FGFRL1 associated with height, hypertension and osteoporosis." (PMID 35980984, 2022). "Therefore, we confirmed the replications of the FGFRL1 signals and identified that the FGFRL1 gene is associated with giraffe-related characteristics (height, hypertension, and osteoporosis) in the human population." (PMID 35980984, 2022). "Similarly, the FGF2, FGF4, FGF10, FGF18, and FGF22 genes, which showed interactions with the FGFRL1 gene, were associated with height, hypertension, and osteoporosis." (PMID 35980984, 2022). "Finally, we also found that the genes encoding fibroblast growth factor and fibroblast growth factor receptor-like 1 may have positive regulatory effects on the prevalence of hypertension and osteoporosis in Korean adults." (PMID 38831414, 2024). "The functional abnormalities of FGFRL1 contribute to human diseases including congenital disease, hypertension, osteoporosis, degenerative diseases of the central nervous system, and different kinds of tumors." (PMID 40699684, 2025). "A regional plot of the FGFRL1 gene based on height, hypertension, and osteoporosis was drawn using LocusZoom." (PMID 35980984, 2022). "The FGF10, FGF18, FGF2, FGF4, and FGF22 genes, which interact with FGFRL1, were correlated with height, hypertension, and osteoporosis." (PMID 35980984, 2022). "The present study is based not only on the correlation between hypertension and osteoporosis but also on previous studies, which elucidated the molecular mechanism of FGFRL1." (PMID 35980984, 2022). "Specific genetic signals involving the fibroblast growth factor receptor-like 1 (FGFRL1) gene are related to high blood pressure and bone growth in giraffes." (PMID 35980984, 2022). "Moreover, gene-edited mice with the giraffe-type FGFRL1 showed exceptional hypertension resistance and higher bone mineral density." (PMID 40699684, 2025). "Our study validated the correlation between FGFRL1 gene and height, hypertension, and osteoporosis." (PMID 35980984, 2022). "Thus, as the giraffe FGFRL1 gene counteracts the detrimental effects of hypertension, it may hold a clue for treatments to protect humans from the adverse effects of hypertension." (PMID 34367673, 2021).
Hypertension (continued). "The mutant mice with giraffe-type FGFRL1 exhibited improved heart function and significantly less fibrosis in cardiac and renal tissues than wild-type mice in response to infusion with angiotensin II, indicating a role for FGFRL1 in suppressing fibrosis in the physiological setting of hypertension." (PMID 34447575, 2021).
prostate carcinoma (6 papers, 2020 to 2025). A carcinoma that arises from epithelial cells of the prostate gland. "These in vitro results could reflect the consequences of the loss of membranous FGFRL1 functions and adoption of other putative intracellular functions in malignant prostate tumors." (PMID 35053442, 2022). "A more detailed analysis of FGFRL1 gene expression in the large MSKCC microarray gene expression data set (218 prostate cancers) showed that FGFRL1 mRNA levels were significantly increased in primary PCa compared to normal prostate, and further increased in advanced and metastatic PCa." (PMID 35053442, 2022). "In bladder cancer, miR-210-3p has been evidenced to inhibit tumor growth by targeting fibroblast growth factor receptor-like 1 (FGFRL1) and promote prostate cancer cell epithelial–mesenchymal transition (EMT) and bone metastasis by targeting the NF-kB signaling pathway." (PMID 34440422, 2021). "The upregulated gene set included oncogenes such as PIK3CB, FGFRL1, and NCOA2; prostate cancer-related genes such as SPON2, PCAT4, and SCHLAP1; and cell cycle genes such as MKI67, MCM4, KIF4A, CENPF, and FLNB." (PMID 38067373, 2023). "Fibroblast growth factor receptors (FGFRs) 1–4 are involved in prostate cancer (PCa) regulation, but the role of FGFR-like 1 (FGFRL1) in PCa is unclear." (PMID 35053442, 2022).
esophageal squamous cell carcinoma (5 papers, 2012 to 2025). Esophageal squamous cell carcinoma (ESCC) is a type of esophageal carcinoma (EC) that can affect any part of the esophagus, but is usually located in the upper or middle third. "Fibroblast growth factor receptor like 1 (FGFRL1) is an mRNA which can cause oncogenous possibility of cells in esophageal squamous cell carcinomas." (PMID 31919528, 2020). "Other miRNAs profiled included miR-210, which is expressed approximately twofold greater in nodular vs. infiltrative tumors and causes reduced progression in esophageal squamous cell carcinomas at least in part by down-regulating fibroblast growth factor receptor like-1 (FGFRL-1)." (PMID 22384406, 2012). "In esophageal squamous cell carcinoma (ESCC) cells, FGFRL1 deficiency decreases tumor growth in xenografts, and its expression is increased in clinical ESCC tumors." (PMID 35053442, 2022). "The downregulation of FGFRL1 was also proven to induce cell cycle arrest and apoptosis in human esophageal squamous cell carcinoma (ESCC) cell lines and human small cell lung cancer (SCLC) cell lines." (PMID 40699684, 2025). "Sixty-nine patients with esophageal squamous cell carcinoma (ESCC) were evaluated for FGFRL1 expression by tissue microarray and compared with the clinicopathological factors of patients." (PMID 40699684, 2025). "It was reported that downregulation of FGFRL1 decreased cell proliferation by promoting the proportion of cells in G1/G0 phase and decreasing in S and G2/M phases in human laryngocarcinoma cancer and esophageal squamous cell carcinoma." (PMID 29675438, 2018).
osteoporosis (4 papers, 2022 to 2025). A condition of reduced bone mass, with decreased cortical thickness and a decrease in the number and size of the trabeculae of cancellous bone (but normal chemical composition), resulting in increased fracture incidence. "Gene mutation or aberrant expression of FGFRL1 is closely associated with a variety of human diseases including congenital disease hypertension, osteoporosis, degenerative diseases of the central nervous system, and different kinds of tumors." (PMID 40699684, 2025). "In humans, FGFRL1 mutation or deletion was proven to be associated with skeletal malformations and osteoporosis." (PMID 40699684, 2025). "Our study suggests that both FGFRL1 and FGFRL1-related genes may determine the height and the prevalence of osteoporosis and hypertension in the Korean population." (PMID 35980984, 2022).
bladder cancer (3 papers, 2021 to 2025). "All these results indicate that FGFRL1 can promote bladder cancer growth and metastasis in vitro and in vivo, and miR-210-3p plays an important role in the inhibition of bladder cancer growth and metastasis through targeting FGFRL1." (PMID 40699684, 2025). "Furthermore, miR-210-3p was shown to regulate bladder cancer growth, invasion, and metastasis by targeting FGFRL1." (PMID 38544804, 2024).